TFPI (tissue factor pathway inhibitor)
Diseases named in the same sentence as TFPI in open-access papers (continued):
Sharing a sentence is not in itself a finding about the gene and the disease.
ischemic stroke (6 papers, 2012 to 2025). A stroke disorder caused by obstruction of blood flow to the brain, due to thrombotic (local blood clot formation) or embolic (due to a blood clot or other material traveling from another site) event. "The 6 pQTLs that were associated with ischemic stroke risk (tissue factor pathway inhibitor, HMWK, prothrombin, prekallikrein, factor XI, and soluble PROCR) were all associated with VTE." (PMID 40188416, 2025). "Thus, in ischemic stroke miR-19a may modulate thrombus formation through effects on TFPI." (PMID 24911610, 2014).
lung carcinoma (6 papers, 2008 to 2021). "Because non-small cell lung cancer (NSCLC) constitutes 85% of lung cancer, the aim of this study was to explore the clinical prediction of TFPI-1 for NSCLC patients with DVT and tumor metastasis." (PMID 28246607, 2017). "The aim of this study is to assess the predicting significance of TFPI-1 for thrombotic complication and metastasis in lung cancer patients." (PMID 28246607, 2017). "But for the inhibitor of TF-factor/VIIa, there were little studies focus on the relationship between TFPI-1 and the progression of lung cancer." (PMID 28246607, 2017). "An 8-marker model was developed (TFPI, MDK, OPN, MMP2, TIMP1, CEA, CYFRA 21–1, SCC) which accurately distinguished subjects with lung cancer (n = 50) from high risk smokers (n = 50) in an independent validation study (AUC = 0.775)." (PMID 26279647, 2015). "Furthermore, although we did not measure the direct markers of coagulation activation, we have found that TFPI-1 was significantly correlated to the indirect markers and closely associated with DVT and tumor metastasis, which revealed its clinical predicting values in lung cancer patients." (PMID 28246607, 2017).
acute coronary syndrome (5 papers, 2010 to 2023). Signs and symptoms related to acute ischemia of the myocardium secondary to coronary artery disease. "Furthermore, subsequent elevated IL-6 levels in the course of acute coronary syndromes are associated with initial TFPI-FXa concentrations." (PMID 22518344, 2012). "Previous studies with observations of increased amounts of free and total TFPI in CAD have mainly focused on patients with acute coronary syndrome while sparse studies include patients with stable angina." (PMID 28115916, 2017). "Another study carried out in France screened the TFPI gene, V264 M for point sequence variations among patients with acute coronary syndrome." (PMID 28716011, 2017). "Elevated TFPI-FXa and prothrombin fragments F1+2 plasma levels indicate activation of the coagulation cascade in acute coronary syndromes." (PMID 22518344, 2012). "Activation of coagulation as measured by TFPI-FXa but not by F1+2 is associated with plasma concentrations of the proinflammatory cytokine IL-8 in acute coronary syndromes." (PMID 22518344, 2012). "Since TFPI has an important role in modulating the activity of the TF:FVIIa complex, recombinant human TFPI might be useful in patients with acute coronary syndromes." (PMID 22043208, 2010). "Unfortunately, the result did not demonstrate that the variations of TFPI contribute to acute coronary syndromes." (PMID 28716011, 2017).
Hypercholesterolemia (5 papers, 2013 to 2023). An increased concentration of cholesterol in the blood. "The unbound form of TFPI is transferred to the LDL-C in a hypercholesterolemia state, and this transfer consequently causes a reduction in endothelial cell-associated TFPI and leads to a hypercoagulable status." (PMID 37590192, 2023). "As an underlying mechanism for the association between blood lipid levels and hemostasis factors, a previous study suggested that hypercholesterolemia may affect the regulation of blood coagulation via tissue factor pathway inhibitor (TFPI)." (PMID 36544148, 2022). "Analysis of Open Targets and other databases indicated evidence of drug development, including phase II-IV trials, for 6 proteins (PGF, ASGR1, F2R, TFPI, tenascin, and MMP3), with 3 related to CVD outcomes or traits (F2R for MI, TFPI for ICH, and ASGR1 for familial hypercholesterolemia)." (PMID 37940228, 2023).
melanoma (5 papers, 2014 to 2022). A malignant, usually aggressive tumor composed of atypical, neoplastic melanocytes. "TFPI is known to be involved in the formation of matrix-rich vascular-like networks in melanoma and is used as a diagnostic marker for SCC." (PMID 28982115, 2017). "Using WGCNA combined with supervised machine learning algorithms, we identified a novel CAFs-related panel, including six genes (CDK14, SYNPO2, TCF4, GJA1, CPXM1, TFPI), which can distinguish the response of melanoma patients under anti-PD-1 immunotherapy." (PMID 35479936, 2022). "It has been demonstrated that TFPI regulates the procoagulant function of TF in highly aggressive melanoma and this activity is essential for the perfusion of vasculogenic mimicry channels formed by TF-expressing melanoma cells." (PMID 33947134, 2021). "Moreover, the presence of TFPI has been found in malignant melanoma cells." (PMID 33947134, 2021).
Obesity (5 papers, 2017 to 2025). Accumulation of substantial excess body fat. "Obesity is associated with increased concentrations of coagulation inhibitors, such as protein C, AT, and Tissue Factor Pathway Inhibitor (TFPI)." (PMID 40871683, 2025). "Interestingly, a correlation between TFPI levels and BMI has been previously reported, demonstrating that an increased obesity index is associated with elevated TFPI levels." (PMID 35783839, 2022). "The observation that the strongest signal in this analysis (ADTRP) is a potent activator of the TFPI gene, which is the second strongest signal in the analysis further strengthens the hypothesis that obesity and testosterone related pathways may modify fibroid risk through these genes." (PMID 28715450, 2017). "Significantly higher concentrations of TF and lower TFPI concentrations were noted in the study group as compared with controls, regardless of coexisting obesity and cardiovascular diseases (P<0.0001 respectively)." (PMID 29475895, 2018). "The mechanistic relationships between obesity, androgens, ADTRP, TF and TFPI have not been studied in relation to uterine fibroids, and the relationships we detect here require additional functional studies." (PMID 28715450, 2017).
Thrombocytopenia (5 papers, 2021 to 2025). A reduction in the number of circulating thrombocytes. "Coagulation-related mediators—including Tissue factor (TF) and Tissue factor pathway inhibitor (TFPI)—also increased, despite the rarity of hemorrhagic events or thrombocytopenia." (PMID 41012652, 2025).
type-2 diabetes (5 papers, 2010 to 2023). "Genetic variations in the TF and TFPI genes seem to be associated with gender and type-2 diabetes, partly affecting their respective phenotypes." (PMID 20444258, 2010). "In addition, genetic polymorphisms of the TFPI gene are likely to be related with type 2 diabetes mellitus in CAD patients." (PMID 28716011, 2017). "Within CKB, TFPI, PGF, F2R, and ASGR1 were each significantly associated with all 4 CVD risk factors (smoking, SBP, adiposity, and type 2 diabetes)." (PMID 37940228, 2023). "In summary, our results, for the first time, demonstrate that AngII promotes the anticoagulant effects of rivaroxaban via AT2R and Mas signaling in an experimental mouse model with type 2 diabetes mellitus, and TFPI is likely a key mediator." (PMID 28337024, 2017). "Moreover, FURIN, ASGR1, SORT1, TFPI, PGF, F2R, and EFNA1 were also associated with SBP, adiposity, and type 2 diabetes." (PMID 37940228, 2023).
Arterial thrombosis (4 papers, 2013 to 2025). The formation of a blood clot inside an artery. "CatG and NE along with neutrophil-derived externalized nucleosomes (which form NETs) have been identified to stimulate coagulation via destruction and inactivation by proteolysis of the tissue factor pathway inhibitor (TFPI), which is an endogenous anticoagulant, resulting in arterial thrombosis." (PMID 34869231, 2021).
colon cancer (4 papers, 2009 to 2024). "Stratifying the neoplastic cohort according to cancer type, patients with CC showed the highest levels of FVIIa-AT, FVII Ag, and total and free TFPI, while subjects with colon cancer had the lowest levels of EV-associated TF-dependent procoagulant activity." (PMID 38282902, 2024). "Given that, pathologically, human solid tumours such as colon cancer are characterised by desmoplasia and tumour stroma has been compared to a 'wound that does not heal', it is perhaps unsurprising that the interaction of TFPI and TF-VIIa has been implicated in tumour cell adhesion and migration." (PMID 19200380, 2009). "Most cancers, including non-small cell lung cancer, renal, breast, and colon cancer, have not been shown to express TFPI in association with tumor cells." (PMID 33947134, 2021).
diabetes (4 papers, 2010 to 2019). "And we found that the investigated genetic polymorphisms of the TFPI genes seemed to be related with diabetes mellitus in our enrolled CAD Han Chinese patients." (PMID 28716011, 2017). "The results of the present study indicate differences in frequencies of the TF polymorphisms as related to diabetes and gender, and additionally changes in plasma levels according to the different TF and TFPI SNPs." (PMID 20444258, 2010). "Hence, we further investigated whether certain selected SNPs in the TFPI gene was related with cardiovascular risk factors (e.g. gender, smoking, medical history of hypertension, diabetes mellitus and hyperlipidemia) among our enrolled participants." (PMID 28716011, 2017). "In stratified analyses based on gender, smoking, hypertension, diabetes mellitus and hyperlipidemia, we further determined that the investigated genetic variations of the TFPI genes seemed to be related with diabetes mellitus in CAD patients." (PMID 28716011, 2017). "Due to the influence of diabetes mellitus, a significant difference in the frequencies of TFPI SNPs was obtained in individuals with CAD compared to controls without CAD in our study." (PMID 28716011, 2017). "Most previous studies supported that the higher levels of TFPI is associated with male gender, increased LDL, smoking and diabetes, all of which are widely accepted as cardiovascular risk factors." (PMID 28716011, 2017). "These genotypes and the phenotypes (TF, TFPI free and total antigen) were evaluated with special reference to gender and diabetes in the CHD population." (PMID 20444258, 2010). "Furthermore, association studies demonstrated that TFPI was significantly higher with older age, male gender, increased low-density lipoprotein(LDL), current smoking and diabetes." (PMID 28716011, 2017). "The observed lower TFPI total antigen in the present study in women with diabetes was only significant for the TFPI -399 CC and the TFPI -287 TT genotypes, which my indicate that the regulation of TFPI by hyperglycemia to some degree is related to the TFPI genotype." (PMID 20444258, 2010). "Thus, a possible enlargement of a TF/TFPI ratio due to genetic variants, may contribute to a hypercoagulable state in CHD, which may be more important for clinical events in women with diabetes." (PMID 20444258, 2010). "Women presenting with T2DM showed a different pattern in TF and TFPI genotypes, as compared to women without diabetes, partly related to their respective phenotypes." (PMID 20444258, 2010).
hyperlipidemia (4 papers, 2017 to 2022). "Increased TFPI activity was found in patients with hyperlipidemia, and there are positive correlations between plasma TFPI activity and total cholesterol as well as LDL cholesterol levels." (PMID 36544148, 2022). "Studies have shown elevated levels of TFPI in patients with peripheral arterial disease of the lower limbs, Buerger's disease, hyperlipidaemia, coronary heart disease and diabetes." (PMID 28749986, 2017). "Studies by Saito and colleagues, however, revealed significantly higher concentrations of TF and TFPI among people with hyperlipidaemia who showed no signs of cardiovascular disease." (PMID 28749986, 2017).
pancreatic cancer (4 papers, 2017 to 2023). "In this study, we present the impact of the analytical variables CTI, anti-TFPI-abs and phospholipids (MP-reagent) on MV-associated thrombin generation in patients with pancreatic cancer and in healthy controls." (PMID 28910348, 2017). "The presence of anti-TFPI abs increased the MV-associated thrombin generation in both groups, and we found significant differences between the pancreatic cancer patients and the healthy controls for all thrombin generation parameters." (PMID 28910348, 2017). "The aim of this study was to describe the effect of CTI, anti-TFPI abs and phospholipids (MP-reagent) on the MV-associated thrombin generation in samples from patients with pancreatic cancer and healthy controls, and find the best conditions to compare these two groups." (PMID 28910348, 2017). "In contrast, TFPI mRNA and protein have been observed in colon, breast, and pancreatic cancer cell lines." (PMID 33947134, 2021). "Using TF and TFPI activity assays, we measured and compared the TF and TFPI activities of AT-84 cells to those of a mouse pancreatic cancer cell line (Hight TF Panc02 cells) which had elevated TF activity and low to moderate TFPI activity." (PMID 33668375, 2021). "With our optimized assay conditions (-CTI, -PS, +anti-TFPI abs), we showed a significantly different procoagulant potential of MVs from patients with pancreatic cancer compared with MVs from healthy individuals." (PMID 28910348, 2017). "Addition of anti-TFPI abs shortened the LTs significantly in both the pancreatic cancer and the healthy control group, and it also reduced the variability between individuals in both groups, most evidently within the healthy group." (PMID 28910348, 2017). "Thus, the addition of anti-TFPI abs to PNP without CTI, and without an MP-reagent, seemed to be the best condition to describe MV-associated thrombin generation in patients with pancreatic cancer and healthy individuals." (PMID 28910348, 2017). "The most favorable analytical condition to measure MV-associated thrombin generation in patients with pancreatic cancer and healthy controls was to add the isolated MVs into low contact-activated PNP without CTI and without external phospholipids, but in the presence of anti-TFPI antibodies." (PMID 28910348, 2017).
preeclampsia (4 papers, 2014 to 2023). Preeclampsia is a hypertensive disorder of pregnancy that is characterized by new-onset hypertension with proteinuria presenting after 20 weeks of gestation, and depending on mild or severe forms may initially present with severe headache, visual disturbances, and hyperreflexia. "Another study also showed that TFPI concentration was significantly higher in samples from patients with preeclampsia compared with normal pregnancies (median, 87.5 ng/mL vs. 66.1 ng/mL)." (PMID 37238908, 2023). "Different profiles of maternal plasma tissue factor and TFPI concentrations have been observed among several obstetrical syndromes including preeclampsia, preterm prelabor rupture of membranes, and small for gestational age." (PMID 29867970, 2018). "The lower TFPI/TF ratio in patients with preeclampsia occurs despite the increase in the median maternal plasma TFPI concentration observed in these patients." (PMID 25426334, 2014). "The median maternal plasma TFPI concentration increases during preeclampsia, which is associated with an exaggerated maternal systemic inflammatory response." (PMID 25426334, 2014). "As plasma TFPI is increased and placental growth factor (PlGF) is decreased in women with preeclampsia, the TFPI-to-PlGF ratio may be useful as a predictive marker for early prediction of preeclampsia." (PMID 37238908, 2023). "In contrast to preeclampsia, maternal plasma TFPI concentration decreases in patients with PTL and preterm PROM regardless to the presence of intra-amniotic infection/inflammation, as well as in women with fetal demise, and does not change in mothers with SGA fetuses." (PMID 25426334, 2014). "Indeed, patients with vascular complications of pregnancy (preeclampsia, eclampsia, placental abruption, fetal growth restriction, and fetal demise) have a lower placental concentration of total TFPI, and TFPI mRNA expression than in women with normal pregnancies." (PMID 25426334, 2014). "To date, however, no articles have compared total TFPI, free TFPI1, and free TFPI2 in plasma, platelets, and placental tissues of women with normal pregnancy and preeclampsia." (PMID 37238908, 2023).
venous thromboembolism (4 papers, 2012 to 2024). Occlusion of the lumen of a vein by a thrombus that has migrated from a distal site via the blood stream. "Protein S enhances TFPI action, and studies have shown that, outside of pregnancy, modulation of TFPI rates is responsible for the increased risk of venous thromboembolism, particularly in women taking oral contraceptives." (PMID 28328938, 2017). "Moreover, higher levels of TFPI were found to be associated with an increased risk for venous thromboembolism and all-cause mortality in 898 cancer patients." (PMID 39624584, 2024).
bladder cancer (3 papers, 2015 to 2022). "On the other hand, over-expression of either human TFPIβ (TFPI) or a mouse TFPIβ (mTFPI), but not TFPI2, elevated the sensitivity to TcdB4.2 in HeLa cells, and in a human bladder carcinoma cell line 5637 (a cell line that we found to be not sensitive to TcdB4.2)." (PMID 36351897, 2022).
bleeding disorders (3 papers, 2018 to 2024). "A full appreciation of TFPI activity has led to the development of specific inhibitors for the management of hemophilia-associated bleeding as well as bleeding complications that occur in rare bleeding disorders." (PMID 38662114, 2024). "On the other hand, suppressor mechanisms are known to regulate coagulation, with AT and TFPI acting as two of the important inhibitors of coagulation in this feedback process; therefore, approaches that inhibit AT or TFPI are also expected to achieve hemostatic activity in bleeding disorders." (PMID 31249933, 2018). "High plasma TFPI levels, like we observed in our PFD participants, have also been reported in other bleeding disorders." (PMID 34185390, 2021).
Hyperglycemia (3 papers, 2010 to 2022). An increased concentration of glucose in the blood. "Chronic blood hyperglycemia may result in the glycosylation of albumin, which has been confirmed to promote the production of TFPI in endothelial cells and monocytes." (PMID 28716011, 2017).
Hypertension (3 papers, 2013 to 2026). The presence of chronic increased pressure in the systemic arterial system. "We identified 36 proteins significantly associated with hypertension and observed a characteristic pattern featuring lower Renin, sRAGE, ghrelin, and IL-1RAcP, and higher TFPI, QORL1, HSP70, and C5a in hypertensive individuals." (PMID 42020520, 2026).
metastatic tumor (3 papers, 2011 to 2024). "TFPI reduces tumor cell-induced coagulation activation and lung metastasis, and it has shown inhibitory effect on primary and metastatic tumors in mice." (PMID 33490103, 2020). "These cells are derived from a primary and a metastatic tumor, respectively, and both express endogenous TFPI; the Sum102 cells approximately four times more than the MDA-MB-231 cells." (PMID 21849050, 2011). "Indeed, higher levels of circulating TFPI were observed in patients with metastatic disease compared to patients with non-metastatic disease in the same study." (PMID 38891849, 2024).